SIRT7 (sirtuin 7)
Diseases named in the same sentence as SIRT7 in open-access papers (continued):
Sharing a sentence is not in itself a finding about the gene and the disease.
melanoma (continued). "However, in melanoma cells, SIRT7 seems to function independently of MEF2D, underscoring its ability to exert opposing effects on the same molecular pathways depending on the specific context." (PMID 38383727, 2024). "Thereafter, we went on to investigate the actual role of SIRT7 in melanoma." (PMID 36918544, 2023). "Unexpectedly, the knockdown of SIRT7 exerted a marginal effect on either cell viability in a short term or cell proliferation in a long term as revealed by CCK8 and colony formation assay, respectively, indicating that SIRT7 was dispensable for melanoma cell proliferation under normal condition." (PMID 36918544, 2023). "Moreover, SIRT7 expression was significantly higher in melanoma than in nevus in Talantov dataset (GDS1375)." (PMID 36918544, 2023). "Since our genomic analysis in the TCGA SKCM database and qRT-PCR assay in melanoma cell lines both pointed out that the up-regulation of SIRT7 occurred at the transcriptional level, we thus went on to figure out the upstream transcriptional factor responsible for this." (PMID 36918544, 2023). "Therefore, NF-κB p65 contributes to SIRT7 up-regulation under stress in melanoma via transcriptional regulation." (PMID 36918544, 2023). "Our present study proved that SIRT7 plays an oncogenic factor in melanoma by synergistically modulating tumor cell survival and anti-tumor immune surveillance, underpinning SIRT7 as a promising therapeutic target, as well as extending the spectrum of cancers that SIRT7 plays a pathogenic role in." (PMID 36918544, 2023). "Regarding SIRT7 being a stress-responsive factor according to our results, we turned to figure out whether SIRT7 plays a regulatory role in melanoma cells upon exogenous stress." (PMID 36918544, 2023). "Thereafter, we also examined the expression status of SIRT7 under normal conditions in melanoma." (PMID 36918544, 2023). "Nevertheless, whether SIRT7 regulates tumor cell biology and tumor immunology in melanoma under stressful tumor microenvironment remains elusive." (PMID 36918544, 2023). "In parallel, the overexpression of SIRT7 in WM35 melanoma cell line resulted in up-regulation of IRE1α expression, IRE1α phosphorylation, spliced XBP1 expression, and HSPA5 expression caused by TM treatment, but marginal influence on ATF6 and phosphorylated-PERK." (PMID 36918544, 2023). "Besides, we also referred to the Gene Expression Omnibus (GEO) melanoma dataset (GSE19234) to analyze the relationship between SIRT7 expression and tumor stress status." (PMID 36918544, 2023). "It should be noted that SIRT7 was prominently up-regulated in metastatic melanoma compared with primary melanoma, which prompted us to see whether SIRT7 had an impact on melanoma cell invasion or migration." (PMID 36918544, 2023). "In addition, the knockdown of MEF2D displayed a marginal effect on PD-L1 expression in SIRT7-overexpressed melanoma cells under TG treatment." (PMID 36918544, 2023). "Targeting SIRT7 could be employed as a promising strategy to restrain tumor growth and increase immunotherapy efficacy in melanoma." (PMID 36918544, 2023). "Moreover, immunohistochemical analysis in TMA revealed that the staining intensity of SMAD4 was down-regulated in melanoma compared to nevus, and the staining intensities of SIRT7 were negatively correlated with that of SMAD4." (PMID 36918544, 2023). "SIRT7 was highly expressed in melanoma tissues than in the control group." (PMID 33274232, 2020). "Therefore, this evidence suggests that the miR-148b/SIRT7 axis has a significant role in the progression of melanoma." (PMID 33274232, 2020). "The proliferation and metastasis of melanoma cells could be inhibited by miR-148b binding to the 3′UTR of SIRT7." (PMID 33274232, 2020).
melanoma (continued). "Moreover, we also examined the interaction between K63-linked ubiquitin chain and SMAD4 after the intervention of SIRT7 in either A2058 or WM35 melanoma cells, and there was no prominent alteration." (PMID 36918544, 2023). "As a result, the suppressive role of SIRT7 knockdown on melanoma growth was partially abrogated as shown by the alterations of tumor volumes and tumor weights, proving that SIRT7 up-regulation contributed to melanoma growth by disrupting CD8+T cells-mediated immunosurveillance." (PMID 36918544, 2023). "In addition to the previous pre-clinical xenograft tumor model, we also subcutaneously injected B16F10 melanoma cells with or without SIRT7 deficiency into immune-competent C57B6/L mice to see the effect on tumor growth." (PMID 36918544, 2023). "However, the role of SIRT7 in melanoma remains poorly elucidated." (PMID 33274232, 2020). "Interestingly, the initial level of miR-148b was greatly declined in melanoma, which might account for the anti-miR-148b inability to raise the level of SIRT7." (PMID 33274232, 2020). "Through qRT-PCR analysis of all sirtuins family members in A2058 melanoma cells treated with TM or HBSS, it was found that SIRT7 displayed the most prominent up-regulation than other members of sirtuins." (PMID 36918544, 2023). "We previously proved that SIRT7 selectively activated the IRE1α-XBP1 axis to simultaneously regulate downstream ERK signal and secretion of cytokines, thus enabling melanoma cell survival under ER stress." (PMID 36918544, 2023). "Then, we proved that SIRT7 enabled melanoma cell survival under stress, and the selective activation of the IRE1α-XBP1 branch of UPR and downstream ERK pathway driven by SIRT7 up-regulation was responsible for this effect." (PMID 36918544, 2023). "For further verification, immunohistochemical staining analysis of SIRT7 was performed via the employment of a tumor tissue microarray (TMA) containing 18 melanocytic nevus tissues, 62 primary melanoma tissues, and 20 metastatic melanoma tissues." (PMID 36918544, 2023). "We treated SIRT7-overexpressed melanoma cell with IRE1α inhibitor STF083010 or the transfection with siRNA against XBP1, which displayed that the up-regulation of PD-L1 by SIRT7 was significantly suppressed at both mRNA and protein levels under ER stress." (PMID 36918544, 2023). "To this end, we established the pre-clinical tumor model via subcutaneously implanting B16F10 melanoma cells into C57BL/6 mice with or without the knockdown of SIRT7 and the mice then received the intraperitoneal injection with anti-PD-1 antibody." (PMID 36918544, 2023). "Collectively, our data proposed the model that SIRT7 deacetylated SMAD4 to trigger its ubiquitination and degradation, thereby relieved the transcriptional suppression on IRE1α to activate IRE1α-XBP1 axis and defend against ER stress in melanoma." (PMID 36918544, 2023). "Intriguingly, it was found that the knockdown of SIRT7 only impaired the activation of ERK after the treatment with TM, whereas displayed little effect on either the phosphorylation of JNK or p38 MAPK in A2058 melanoma cell." (PMID 36918544, 2023). "Transwell assay proved that SIRT7 deficiency showed little effect on the invasion or migration of melanoma cells, indicating that SIRT7 probably did not play a role in regulating melanoma metastasis." (PMID 36918544, 2023). "We treated TM-stimulated melanoma cells with NF-κB p65 inhibitor APDC, and the up-regulation of SIRT7 was prominently impaired, raising the notion that NF-κB p65 also contributed to SIRT7 up-regulation under stress." (PMID 36918544, 2023). "The present study demonstrated for the first time that miR-148b expression was significantly downregulated while SIRT7 was upregulated in human melanoma cells unlike in melanocytes and benign nevi." (PMID 33274232, 2020).
melanoma (continued). "The selective regulation of ERK rather than JNK or p38 MAPK after the intervention of SIRT7 under stress might be due to different characteristics of IRE1α function between melanoma cells and other types of cells." (PMID 36918544, 2023). "Therefore, the regulation of PD-L1 by SIRT7 is independent of MEF2D, and the regulatory mechanism of MEF2D by SIRT7 does not exist in melanoma cells under ER stress." (PMID 36918544, 2023). "Nevertheless, whether SIRT7 participates in regulating tumor cell biology and anti-tumor immunity in melanoma, especially under the circumstance of stressful TME, has not been investigated." (PMID 36918544, 2023). "Notably, the effect of SIRT7 on PD-L1 expression in melanoma cells under non-stressed conditions is negligible, indicating that, in this malignancy, SIRT7 governs PD-L1 expression through distinct cancer-cell-type-specific regulatory circuits shaped by microenvironmental cues." (PMID 41471367, 2025). "To prove that the selective activation of the IRE1α-XBP1 axis and IRE1α-dependent ERK activation accounted for the protective role of SIRT7 under stress, we employed colony formation assay by using WM35 melanoma cells with or without SIRT7 overexpression." (PMID 36918544, 2023). "Moreover, we also employed immunohistochemical staining analysis in TMA to examine the relationship between tumorous SIRT7 expression and CD8+T cells infiltration, which revealed the negative correlation between SIRT7 and CD8 in melanoma tissues." (PMID 36918544, 2023).
Hyperglycemia (6 papers, 2014 to 2024). An increased concentration of glucose in the blood. "Since our data establish a causal relationship and implicate Sirt7 as a regulator of the insulin/IGF pathway, our data may also suggest a role of Sirt7 in hyperglycemia associated with chemoresistance." (PMID 24885964, 2014). "SIRT7 plays a protective role under these conditions; the upregulation of miR-20b in podocytes targets SIRT7 to promote apoptosis during hyperglycemia." (PMID 37676263, 2024). "In summary, the present study indicates that SirT7 transcribesfascin to contribute to hyperglycemia-induced EndMT in DN patients." (PMID 38449390, 2024). "This study demonstrated that the hyperglycaemia‐mediated interaction between Sirt7 and HIC1 exerts a role in the metabolic memory in DKD by inactivating SDC1 transcription and mediating EndMT despite glucose normalization in HGECs." (PMID 38686489, 2024). "Moreover, SirT7-mediated histone acetylation participates in hyperglycemia-mediated endothelial inflammation." (PMID 38449390, 2024). "Moreover, SirT7-mediated histone acetylation is involved in hyperglycemia-mediated endothelial inflammation via modulation of death-associated protein kinase 3 transcription." (PMID 38449390, 2024). "Our data indicated a downregulation of hyperglycaemia‐induced αSMA by Sirt7 overexpression supplemented with glucose normalization, which increased the hyperglycaemia‐mediated reduction of HIC1, SDC1 and CD31 expression in the kidneys of the rats, while insulin alone did not work." (PMID 38686489, 2024). "To encapsulate, our findings suggest that hyperglycaemia triggers a mutual regulation between Sirt7 and HIC1 that persists even after glucose levels normalize, thereby establishing a positive feedback loop that contributes to the development of metabolic memory." (PMID 38686489, 2024). "Hyperglycemia upregulates expression of miR-125b-5p mediated by Janus kinase (JAK)/signal transducer and activator of transcription (STAT) signaling, which inhibits SIRT7 and promotes myeloid cell-driven coronary calcification in diabetic individuals." (PMID 37676263, 2024).
myocardial infarction (6 papers, 2017 to 2023). Gross necrosis of the myocardium, as a result of interruption of the blood supply to the area, as in coronary thrombosis. "The activation of autophagy was found to reduce fibroblast differentiation and myocardial infarction-related cardiac fibrosis were observed in the SIRT7 KO mice and SIRT7 KO mouse-derived cardiac fibroblasts." (PMID 32724454, 2020). "SIRT7 expression is increased in response to acute cardiovascular injury, including myocardial infarction and hind-limb ischemia, particularly at the active wound healing site." (PMID 31858380, 2020). "Decreased expression of inflammation-related genes is also detected in the heart of Sirt7 KO mice after myocardial infarction and in the white adipose tissue of high-fat diet-fed Sirt7 KO mice." (PMID 29651144, 2018).
osteosarcoma (6 papers, 2014 to 2025). A usually aggressive malignant bone-forming mesenchymal neoplasm, predominantly affecting adolescents and young adults. "In osteosarcoma cells, knocking down SIRT7 decreased proliferation, migration, invasion, and growth, whereas overexpression had the opposite effects." (PMID 41304967, 2025). "SIRT1, SIRT2, SIRT6 and SIRT7 proteins are mainly localized in the nucleus or cytoplasm and are more likely to play important roles in the development of osteosarcoma." (PMID 36344502, 2022). "Previous reports have shown that SIRT6 and SIRT7 proteins were elevated in osteosarcoma cells, and they promoted the migration and invasion of osteosarcoma cells by different mechanisms." (PMID 36344502, 2022). "Besides, lncRNA AC007207.2 drove the upregulation of SIRT7 by sponging miRNA-1306-5p in osteosarcoma cells, while lincRNA p21 elevated SIRT7 levels by sponging miRNA-17-5p in vascular smooth muscle cells." (PMID 37191431, 2023). "SIRT7 accelerates the proliferation, migration, and invasion of osteosarcoma cells through the inhibition of CDC4, suggesting that SIRT7 could serve as a potential therapeutic target." (PMID 41304967, 2025).
steatosis (6 papers, 2015 to 2023). Increased lipid within the cytoplasm of cells. "Another study reported that SIRT7 deficiency produced hepatic microvesicular steatosis, with elevated plasma triglycerides and free fatty acids, and linked it to impaired mitochondrial function." (PMID 35585284, 2022). "TR4 levels are reduced in SIRT7-deficient liver, and the steatosis-resistant phenotype could be explained by a decreased expression of lipid synthesis and storage genes." (PMID 25654079, 2015). "Because SIRT7 increases GABP activity by deacetylating GABPβ1, aged Sirt7 KO mice are reported to exhibit hepatic microvesicular steatosis due to mitochondrial dysfunction." (PMID 38201252, 2023). "SIRT7 modulated ER stress activation and prevented hepatic steatosis by inhibiting the transcription factor Myc." (PMID 35743232, 2022). "In another study, Ryu and colleagues generated a different Sirt7 knockout mouse (deleting exons 6–9), and likewise observed that these suffered from liver microvesicular steatosis, with elevated plasma TG and free fatty acids." (PMID 25654079, 2015). "Aged Sirt7 KO mice exhibit hepatic microvesicular steatosis due to mitochondrial dysfunction." (PMID 36509749, 2022). "In mouse studies, ablation of SIRT1 in the liver or global SIRT7 deletion led to fatty liver under standard diet conditions, and global SIRT3 ablation accelerated steatosis development under HFD." (PMID 35743232, 2022).
asthma (5 papers, 2022 to 2025). "Besides SIRT1, other sirtuins including SIRT2, SIRT3, SIRT6, and SIRT7 have also been linked with asthma." (PMID 41008562, 2025). "Conversely, increased SIRT7 facilitates airway remodeling in asthma by modulating TGF-β1-driven proliferation and migration of airway smooth muscle cells; suggesting a distinct role for SIRT6 in airway remodeling." (PMID 41008562, 2025). "SIRT6 and SIRT7′s expression levels have been elevated in human bronchial epithelial cells which were obtained from asthma patients." (PMID 41008562, 2025). "To assess the role of SIRT6 in the pathogenesis of asthmatic airway remodeling, we initially detected the expression of SIRT6 and other sirtuin deacetylases (SIRT1-SIRT5, SIRT7) in the lung tissues in an experimental model of acute severe asthma (ASA)." (PMID 38135684, 2023). "Furthermore, research on respiratory diseases has shown that SIRT7, which is upregulated in airway epithelial cells from asthma patients, promotes airway remodeling by modulating TGF-β1-induced proliferation and migration of airway smooth muscle cells." (PMID 40884727, 2025). "Further research on the role of SIRT7 in asthma is required to make a conclusive claim." (PMID 36117172, 2022). "Sirtuin 7 (SIRT7), a member of the NAD+‐dependent deacetylase family that also functions as a desuccinylase, has been implicated in multiple pathological conditions, such as cancer, cardiac fibrosis, asthma, gastrointestinal disorders and inflammatory diseases." (PMID 40672112, 2025).
Insulin resistance (5 papers, 2016 to 2025). Increased resistance towards insulin, that is, diminished effectiveness of insulin in reducing blood glucose levels. "In turn, in our study, SIRT7 targeting miR-125a was under-expressed in obese individuals and this finding was consistent with animal studies where down-regulation of this miRNA in murine adipocytes was associated with insulin resistance." (PMID 27104517, 2016). "In summary, EMPA activates NRF1 and SIRT7, reduces lipid accumulation, improves insulin resistance, and suppresses oxidative stress in an HFD-fed mouse model of MASLD." (PMID 40362294, 2025). "Interestingly, miR-378 induces insulin resistance by targeting P110a and SIRT7." (PMID 37342358, 2023).
liver fibrosis (5 papers, 2020 to 2025). "To further investigate the relationship between SIRT7 and the pathological progression of hepatic fibrosis, we analyzed the expression of SIRT7 in clinical samples of human hepatic fibrosis." (PMID 40777599, 2025). "OA binds to the Gln299 and Asp305 residues of SIRT7, triggering a dual regulatory program in hepatic fibrosis." (PMID 40777599, 2025). "In a CCl4-induced mouse model of liver fibrosis, SIRT7 expression in activated HSCs increased with disease progression." (PMID 40777599, 2025). "Hepatic fibrosis as measured with Sirius red staining was reduced in SIRT7−/− mice with ATF3 inactivation." (PMID 36516757, 2022). "Our study has revealed a previously unrecognized molecular link between the deacetylation of RELA and its transcription activity, and expression of target genes by SIRT7, which further regulates the liver inflammation and the development of liver fibrosis in largemouth bass." (PMID 41322258, 2025). "Subsequently, we examined whether the favorable effects on mitigating liver fibrosis and liver inflammation mediated by SIRT7 inhibition is through its influence on the acetylation of RELA." (PMID 41322258, 2025). "Besides, we confirmed that OA has an important anti-liver fibrosis effect, while the overexpression of SIRT7 reversed the effect." (PMID 40777599, 2025). "Meanwhile, a recent study showed that SIRT7 has a beneficial effect on hepatic fibrosis." (PMID 40777599, 2025). "In summary, HFHFD may inhibit liver gluconeogenesis, potentially promoting liver fibrosis by regulating Sirt7 expression." (PMID 38929712, 2024). "Given the potent effects of SIRT7 inhibitor on suppression of LPS-mediated liver inflammation, we examined whether SIRT7 inhibitor could exert a similar role in suppressing liver fibrosis in a fish model induced by chronic inflammation preventing RELA deacetylation." (PMID 41322258, 2025). "We propose a model in which stress promotes RELA nuclear translocation to facilitate the interaction with SIRT7, leading to enhanced RELA deacetylation and the subsequent aggravation of liver inflammation and the development of liver fibrosis." (PMID 41322258, 2025). "As expected, OA did not improve hepatic fibrosis when pretreatment with VA-Lip-SIRT7 plasmid was administered." (PMID 40777599, 2025). "At the same time, compared with the SIRT7-knockdown group, OA treatment in SIRT7-knockdown cells did not further suppress the expression of PRMT5 and liver fibrosis markers." (PMID 40777599, 2025).